BLM (BLM RecQ like helicase)
Description:
ATP-dependent DNA helicase that unwinds double-stranded (ds)DNA in a 3'-5' direction. Participates in DNA replication and repair. Involved in 5'-end resection of DNA during double-strand break (DSB) repair: unwinds DNA and recruits DNA2 which mediates the cleavage of 5'-ssDNA. Stimulates DNA 4-way junction branch migration and DNA Holliday junction dissolution. Binds single-stranded DNA (ssDNA), forked duplex DNA and Holliday junction DNA. Unwinds G-quadruplex DNA; unwinding occurs in the 3'-5' direction and requires a 3' single-stranded end of at least 7 nucleotides. Helicase activity is higher on G-quadruplex substrates than on duplex DNA substrates. Telomeres, immunoglobulin heavy chain switch regions and rDNA are notably G-rich; formation of G-quadruplex DNA would block DNA replication and transcription. Negatively regulates sister chromatid exchange (SCE). Recruited by the KHDC3L-OOEP scaffold to DNA replication forks where it is retained by TRIM25 ubiquitination, it thereby promotes the restart of stalled replication forks (By similarity). (Microbial infection) Eliminates nuclear HIV-1 cDNA, thereby suppressing immune sensing and proviral hyper-integration.
Synonyms: RecQ2; RECQL3; BS; MGRISCE1; RECQL2
Tractability: Small molecule: a structure with a bound ligand is known; a high-quality ligand is known; it belongs to a druggable protein family. PROTAC: UniProt records ubiquitination sites on it; ubiquitination databases record sites on it; a small molecule that binds it is known.
Target class: Enzyme
Chemical probes: ML216
Gene: Protein-coding gene on chromosome 15 (90,717,340 to 90,816,166, forward strand). Ensembl gene ENSG00000197299.
Subcellular location: Nucleus
Subcellular location (Human Protein Atlas): Nucleoplasm; Cytosol
Pathways (Reactome):
DNA Repair: HDR through Homologous Recombination (HRR); HDR through Single Strand Annealing (SSA); Homologous DNA Pairing and Strand Exchange; Presynaptic phase of homologous DNA pairing and strand exchange; Processing of DNA double-strand break ends; Resolution of D-loop Structures through Holliday Junction Intermediates; Resolution of D-loop Structures through Synthesis-Dependent Strand Annealing (SDSA)
Disease: Defective HDR through Homologous Recombination Repair (HRR) due to PALB2 loss of BRCA1 binding function; Defective HDR through Homologous Recombination Repair (HRR) due to PALB2 loss of BRCA2/RAD51/RAD51C binding function; Defective homologous recombination repair (HRR) due to BRCA1 loss of function; Impaired BRCA2 binding to PALB2; Impaired BRCA2 binding to RAD51
Cell Cycle: G2/M DNA damage checkpoint; Processive synthesis on the C-strand of the telomere
Metabolism of proteins: SUMOylation of DNA damage response and repair proteins
Reproduction: Meiotic recombination
Gene Ontology:
Molecular function: 3'-5' DNA helicase activity; 8-hydroxy-2'-deoxyguanosine DNA binding; ATP binding; ATP hydrolysis activity; ATP-dependent activity, acting on DNA; bubble DNA binding; DNA binding; DNA helicase activity; DNA/DNA annealing activity; forked DNA-dependent helicase activity; four-way junction DNA binding; four-way junction helicase activity; G-quadruplex DNA binding; helicase activity; identical protein binding; protein binding; protein homodimerization activity; single-stranded DNA binding; telomeric D-loop binding; telomeric G-quadruplex DNA binding; Y-form DNA binding; zinc ion binding; hydrolase activity, acting on acid anhydrides, in phosphorus-containing anhydrides; nucleic acid binding; and 1 more
Biological process: cellular response to camptothecin; cellular response to hydroxyurea; cellular response to ionizing radiation; DNA damage response; DNA double-strand break processing; DNA geometric change; double-strand break repair via homologous recombination; mitotic G2 DNA damage checkpoint signaling; negative regulation of cell division; negative regulation of DNA recombination; positive regulation of DNA-templated transcription; protein complex oligomerization; protein homooligomerization; regulation of cyclin-dependent protein serine/threonine kinase activity; replication fork processing; resolution of DNA recombination intermediates; response to X-ray; telomere maintenance; telomeric D-loop disassembly; DNA recombination; DNA repair; DNA replication; t-circle formation; telomere maintenance via semi-conservative replication
Cellular component: chromosome, telomeric region; lateral element; nuclear chromosome; nuclear matrix; nucleolus; nucleoplasm; nucleus; PML body; protein-containing complex; RecQ family helicase-topoisomerase III complex; chromosome; cytoplasm; replication fork
Genetic constraint (gnomAD): Loss-of-function variants: 91 observed, 127.95 expected, observed/expected ratio (o/e) 0.71, 90% interval 0.6 to 0.85. The synonymous counts are far from expectation, so gnomAD's model fits this gene poorly and the ratio says little. Missense variants: 1,453 observed, 1,673.4 expected, observed/expected ratio (o/e) 0.87, 90% interval 0.83 to 0.91. Synonymous variants: 494 observed, 596.11 expected, observed/expected ratio (o/e) 0.83, 90% interval 0.77 to 0.89.
Gene-disease validity (ClinGen):
ClinGen rates the evidence that BLM causes each of these diseases.
Bloom syndrome (autosomal recessive): Definitive. Bloom syndrome (BSyn) is a rare chromosomal breakage syndrome characterized by a marked genetic instability associated with pre- and postnatal growth retardation, facial sun-sensitive telangiectatic erythema, increased susceptibility to infections, and predisposition to cancer.
colorectal cancer (autosomal dominant): Limited. A primary or metastatic malignant neoplasm that affects the colon or rectum.
Cancer hallmarks: suppression of growth (promotes); escaping programmed cell death (suppresses); genome instability and mutations (suppresses)
Homologues: Orthologues: chimpanzee BLM (99% identical), macaque BLM (96% identical), pig BLM (84% identical), dog BLM (83% identical), guinea pig BLM (78% identical), mouse Blm (76% identical), rabbit BLM (76% identical), rat Blm (75% identical), tropical clawed frog blm (51% identical), zebrafish blm (46% identical), Drosophila melanogaster Blm (28% identical), Caenorhabditis elegans him-6 (23% identical). Paralogues in human: WRN (18% identical), RECQL (16% identical), RECQL5 (16% identical), RECQL4 (14% identical).
Diseases named in the same sentence as BLM in open-access papers:
BLM is named in the same sentence as 152 diseases in open-access papers, as found by Europe PMC text mining. Sharing a sentence is not in itself a finding about the gene and the disease. The quoted sentences say what the papers report.
Bloom syndrome (197 papers, 2006 to 2026). "Loss of BLM helicase leads to Bloom Syndrome, characterized by genomic instability, cancer predisposition and immunodeficiency." (PMID 42156715, 2026). "Bloom syndrome is a rare autosomal recessive disorder caused by mutations in the BLM gene, which encodes a RecQ helicase crucial for genome stability." (PMID 40641635, 2025). "The TPM3-NTRK fusion has been reported in a case of a child with Bloom syndrome, with the fusion appearing in both BLM alleles." (PMID 40151290, 2025). "Considering that aneuploidy is a hallmark of cancer, we propose that this role for BLM in cytokinesis is a plausible reason for cancer predisposition in Bloom’s syndrome individuals." (PMID 40355560, 2025). "We propose a model in which cytokinesis failure in BLM-deficient cells serves as a mechanism to generate aneuploidy and hence predisposes Bloom’s syndrome sufferers to the development of cancers of many types." (PMID 40355560, 2025). "In the case of Bloom syndrome, caused by loss-of-function mutations in BLM, cell lines derived from both the healthy donor and the BS individual accumulated complex chromosomal aberrations irrelevant to the disease status." (PMID 40155863, 2025). "Homozygous intragenic deletions mediated by Alu–Alu recombination and causing recessively inherited diseases have been reported in BLM, causing Bloom syndrome (MIM 210900), and in SNX14, causing spinocerebellar ataxia (MIM 616354)." (PMID 41438488, 2025). "Loss of BLM function causes Bloom syndrome (BS), while loss of or reduced RECQ4 function is associated with Rothmund–Thomson (RTS), Baller–Gerold, and RAPADILINO syndromes." (PMID 39125869, 2024). "Recently, it was discovered that BLM mutations in the blood of Bloom syndrome patients trigger the activation of the c-GAS-STING pathway, type II IFN responses, and the induction of ISGs." (PMID 38473997, 2024). "Loss-of-function mutations in the BLM gene cause Bloom syndrome, a rare and recessive genetic disorder associated with an increased risk of various types of cancer." (PMID 38341452, 2024). "Homozygous BLM mutations cause a rare autosomal recessive inherited disorder “Bloom Syndrome” that is characterized by chromosomal instability, immunodeficiency, and a predisposition to different types of malignancies, including breast and colon cancers." (PMID 38313678, 2024). "Bloom syndrome (BS) is a rare autosomal recessive disorder caused by a loss-of-function mutation in the BLM gene encoding an RecQ helicase involved in DNA repair and maintenance of chromosomal stability." (PMID 38995367, 2024). "Pathogenic variants in human BLM cause the autosomal recessive disorder Bloom Syndrome, characterized by predisposition to numerous types of cancer." (PMID 38659896, 2024). "BLM mutations are responsible for Bloom syndrome, a genetic disorder characterized by genetic instability and an increased risk of cancer." (PMID 38473997, 2024). "Pathogenic variants in BLM cause Bloom Syndrome, a rare autosomal recessive disorder characterized by a high predisposition to a broad range of cancers, sun sensitivity, short-stature, sterility, and immunodeficiency." (PMID 38659896, 2024). "Nonetheless, Bloom syndrome is caused by pathogenic variants in BLM, a DNA helicase gene that is involved in genome replication, DNA repair, recombination, transcription, and telomere maintenance." (PMID 39063601, 2024). "Das autosomal-rezessiv vererbte Bloom-Syndrom (BS) entsteht durch homozygote Mutationen im BLM-Gen, das für ein RecQ-Helikase-Enzym kodiert." (PMID 37650893, 2023). "The gene encoding the BLM protein is mutated in patients with Bloom's syndrome, displaying high genomic instability and predisposition to cancers." (PMID 37503837, 2023). "Bloom syndrome (BSyn) is an autosomal recessive disorder caused by variants in the BLM gene, which is involved in genome stability." (PMID 37594403, 2023).
Bloom syndrome (continued). "Bloom syndrome (BSyn) is caused by biallelic null variants in BLM, which encodes for a DNA helicase protein in the RecQ family that functions in the maintenance of replication fork stability." (PMID 37594403, 2023). "Mutations in BLM result in Bloom's syndrome, an autosomal recessive disease with abnormal immunoreaction." (PMID 37273692, 2023). "Mutations in BLM, a RecQ-like helicase, have been linked to the autosomal recessive cancer-prone disorder Bloom’s syndrome." (PMID 37875822, 2023). "The frequent pathogenic monoallelic variant BLM p.Tyr736Leufs*5 found in seven participants is a well-known common founder allele in the Ashkenazi Jewish population and is associated with Bloom syndrome." (PMID 36845387, 2023). "Bloom syndrome is an autosomal recessive disorder caused by germline variants in a DNA repair gene called BLM." (PMID 37594403, 2023). "Pathogenic variants affecting the BLM gene are responsible for the manifestation of extremely rare cancer-predisposing Bloom syndrome." (PMID 37052241, 2023). "Recently, novel deep intronic variant leading to a pseudo-exon activation has been detected using RNA-based long-range PCR in an individual with Bloom syndrome and only one causative variant in the BLM gene which was detected in the previous analysis." (PMID 37052241, 2023). "Although its prevalence in the population of Ashkenazi Jews is estimated to be ~1:48,000, only ~1/3 of individuals with Bloom syndrome due to the causative variants in the BLM gene are of Ashkenazi Jewish descent." (PMID 37052241, 2023). "Pathogenic variants in TOP3A can cause a disorder similar to Bloom syndrome, which results from bi‐allelic pathogenic variants in BLM, encoding a nuclear‐binding partner of TOP3A." (PMID 37013609, 2023). "The DNA helicase BLM, whose depletion or mutation causes the cancer-prone Bloom’s syndrome (BS), is a central factor of DNA damage repair by homologous recombination (HR) and genomic stability maintenance." (PMID 36569948, 2022). "recently described an individual with clinical Bloom syndrome who had a deep intronic variant in BLM (c.3020-258A>G, intron 15) along with a nonsense variant in exon 18 (called c.3379C>T, p.Gln1127Ter) on the opposite allele." (PMID 35359366, 2022). "Defects in BLM are associated with the Blooms syndrome, an autosomal recessive disorder featured by chromosome gaps and breaks, elevated sister chromatid exchange, mitotic hyper-recombination, as well as aberrant DNA replication events." (PMID 36389665, 2022). "When this is disrupted, most commonly through LoF mutations in the BLM gene, it results in Bloom syndrome." (PMID 35935937, 2022). "In an evaluation of the 64 different BLM pathogenic mutations reported by individuals in the Bloom Syndrome registry, 54 were variants leading to protein truncation and 10 were missense variants." (PMID 35359366, 2022). "The BLM gene was identified as mutated in persons affected by the autosomal recessive, clinical entity Bloom syndrome." (PMID 35847987, 2022). "For instance, homozygous loss-of-function mutations of BLM cause Bloom’s syndrome which is characterized as premature aging, immune deficiency, and skin lesions." (PMID 35267530, 2022). "Mutations in the BLM gene are the major cause of Bloom syndrome, a rare autosomal recessive genetic disorder characterized by typical premature aging phenotypes." (PMID 36611939, 2022). "Since the discovery of the link between BLM and Bloom syndrome, several human gene–disease associations (GDAs) have been discovered involving DEAD/H-box proteins." (PMID 35626643, 2022). "The Bloom Syndrome helicase (BLM) is a 3’ to 5’ DNA helicase mutated in Bloom Syndrome which is a genetic disorder associated with an increased risk of cancer, sun-induced chronic erythema, impaired fertility, and immune deficiency." (PMID 35440629, 2022).
Bloom syndrome (continued). "Patients with Bloom syndrome, who have BLM germ-line mutation resulting in striking decreases in both mRNA and protein expression levels of BLM, are apt to develop diverse malignancies including breast cancer, prostate cancer, and lung cancer." (PMID 33828983, 2021). "Altogether, DSB repair dysfunction associated with BLM defects underlying the progeria Bloom's syndrome mark a prototypic link between DNA repair changes and aging." (PMID 34506302, 2021). "Mutated helicase BLM causes Bloom syndrome, which is also associated with genomic instability and cancer." (PMID 34139671, 2021). "Loss of function mutations in BLM cause the genetic instability/cancer predisposition syndrome Bloom syndrome." (PMID 34606619, 2021). "Additional alterations were found in BLM, responsible for Bloom syndrome, an autosomal recessive disease associated with a wide range of malignancies (notably carcinomas, hematologic malignancies, and sarcomas)." (PMID 34359575, 2021). "Bloom syndrome (BS) is caused by mutations in BLM, which encodes a RecQ helicase critical for suppressing recombination and thereby genome instability." (PMID 33512317, 2021). "Bloom syndrome is a rare autosomal recessive genetic disorder caused by mutations in the BLM gene encoding BLM RecQ–like helicase, which maintains DNA stability during cell replication." (PMID 34659260, 2021). "BLM deficiency in Bloom syndrome (BS) causes increased expression of inflammatory genes through the cGAS–STING–IRF3 pathway, suggesting it prevents unchecked inflammatory gene responses." (PMID 34970273, 2021). "Biallelic BLM mutation usually occurs in Bloom syndrome, which features abnormal DNA repair and high levels of chromosome breaks and rearrangements." (PMID 34885201, 2021). "Werner Syndrome (WS) and Bloom Syndrome (BS) are disorders of DNA damage repair caused by biallelic disruption of the WRN or BLM DNA helicases respectively." (PMID 32367056, 2020). "Mutations in the BLM gene are associated with Bloom syndrome, which carries a greatly increased risk of cancers including squamous cell carcinoma, leukemia, lymphoma, and gastrointestinal cancer." (PMID 33519915, 2020). "Bloom syndrome (BS) is a rare autosomal recessive genetic disorder caused by pathogenic variants in the BLM gene." (PMID 32704157, 2020). "Bloom syndrome protein exhibits both DNA-stimulated ATPase and ATP-dependent DNA helicase activities, and mutations in BLM cause Bloom syndrome." (PMID 32300589, 2020). "It is not clear which of these activities is most important for the contribution of BLM to maintenance of genomic integrity, and preventing the tumor susceptibility that is characteristic of Bloom Syndrome." (PMID 32369918, 2020). "The RecQ helicase family contains five members, including RecQ1, RecQ2, RecQ4 (mutated in Rothmund–Thomson syndrome), Bloom syndrome (BLM) and Werner syndrome (WRN)." (PMID 32283785, 2020). "Cells homozygous for a BLM mutation (from patients with Bloom syndrome) exhibit chromosomal instability characterized by a high rate of sister chromatid exchanges and vast structural rearrangements." (PMID 31614901, 2019). "This evolutionary conservation also supports the critical role of BLM in maintaining genome integrity in all cells, thus suggesting why the loss of BLM function in Bloom Syndrome patients results in disease associated with high levels of genome instability." (PMID 31772289, 2019). "Homozygous mutations of the BLM gene are the cause of a rare recessive genetic disorder, Bloom syndrome, which is characterized by chromosomal instability, immunodeficiency, and a predisposition to different malignancies, including breast cancer." (PMID 31614901, 2019). "Inherited mutations in RecQ helicases result in Bloom Syndrome (BLM mutation), Werner Syndrome (WRN mutation), Rothmund-Thomson Syndrome (RECQL4 mutation), and other genetic diseases, including cancer." (PMID 31772289, 2019).